IL6 (interleukin 6)
Diseases named in the same sentence as IL6 in open-access papers (continued):
Sharing a sentence is not in itself a finding about the gene and the disease.
keloid (continued). "Using the current KPCs-generated transplant as a keloid model we attempted to treat with IL-6 neutralizing antibody using standard intra-lesional injection approach and showed significant reduction in keloid size." (PMID 19907660, 2009). "More importantly, abundant keloid-like collagen fibrils were accumulated in transplants of KPCs in the presence of IL-6 that resembled the characteristic histological features of keloid scars." (PMID 19907660, 2009). "A robust elevation of IL-6 and IL-17 expression in keloid is confirmed by cytokine array, western blot and ELISA analyses." (PMID 19907660, 2009). "Consistent with previous reports, we have demonstrated that IL-6 is significantly up-regulated in keloid scars versus their normal skin counterparts, and KPCs constitutively express a higher level of IL-6 and IL-6R compared to SKPs." (PMID 19907660, 2009). "The interaction between the keloid niche and keloid derived stem cells, KPCs, has been demonstrated here in our study, which is sustained by the IL-17/IL-6 feedback loop." (PMID 19907660, 2009). "We have also defined an essential inflammatory cytokine paracrine loop between IL-17 and IL-6, constituting the “pathological” keloid niche that is capable of elevating the proliferation-promoting signal." (PMID 19907660, 2009). "The IL-17-triggered positive-feedback loop via paracrine IL-6 induction constitutes the “pathological” niche or altered inflammatory niche that drives KPCs toward proliferation, and thus tumor-like keloid growth." (PMID 19907660, 2009). "However, the specific mechanisms of the targeted effects of quercetin and IL6/HAS2 in the treatment of keloids still need to be further explored." (PMID 41544047, 2026). "Moreover, intralesional injection of calcium antagonists can turn on procollagenase gene expression and inhibit VEGF and IL-6 in keloids." (PMID 41556665, 2026). "Future studies should prioritize experimental validation of AMPH/TNFRSF9 in larger cohorts, functional characterization of IL6/HAS2 in keloid models and development of quercetin topical formulations to address the clinical need for safe and effective anti-keloid treatment." (PMID 41544047, 2026). "This indicates that quercetin might emerge as a promising anti-keloid strategy by mechanistically disentangling IL6-induced ECM dysregulation from the TGF-β-mediated fibrotic cascade." (PMID 41544047, 2026). "IL6 emerged as both a key network hub and a therapeutic target, linking keloid and TCM mechanisms." (PMID 41544047, 2026). "Other research shows that IL-6 serum levels were significantly higher in keloid patients." (PMID 39799030, 2025). "IL-6 and IL-11, two closely related gp130-family cytokines, have emerged as key mediators at the interface of inflammation and fibrosis, providing a mechanistic link that is highly relevant to keloid pathogenesis." (PMID 41562114, 2025). "However, the area surrounding keloid lesions exhibits heightened expression of IL-6, which contributes to keloid formation by inducing STAT3 phosphorylation in fibroblasts." (PMID 38284901, 2024). "While IL-6 can accelerate wound healing by promoting an inflammatory response, it can also stimulate fibroblasts to produce collagen excessively, contributing to scar proliferation and keloid formation when secreted excessively." (PMID 38284901, 2024). "Three major limitations of our study are (i) differences between various ethnic groups in the frequency of the analyzed IL6 and IL6R variants, (ii) differences between ethnic groups in the occurrence of the clinical phenotype of keloids, and (iii) the relatively small size of our sample." (PMID 38791322, 2024). "Studies have also established the critical role of IL-6 in keloid formation." (PMID 38284901, 2024). "In addition, in patients with keloids, the concentration of interleukin-6 in GG homozygotes was significantly higher compared to individuals with the CC homozygous genotype." (PMID 38791322, 2024).
keloid (continued). "Moreover, the reduction of GRHL2 expression can affect the TGF-β, TNF-NFκB, and IL-6 signaling pathways of keratinocytes, thereby potentially influencing their interaction with the keloid microenvironment." (PMID 39402063, 2024). "Additionally, IL-6 treatment of normal fibroblasts increased paxillin alignment, while tocilizumab treatment of keloid fibroblasts decreased paxillin alignment, showing that this response was downstream of IL-6 signaling." (PMID 37660739, 2023). "Previous research has shown that IL-6 expression is increased in keloid fibroblasts." (PMID 37895153, 2023). "We next examined keloid behaviors that may be downstream of IL-6 in controlling the cellular alignment process." (PMID 37660739, 2023). "In addition, many cytokines, such as TGF-β, IL-3, IL-6, and IL-14, are also important factors in promoting keloid formation." (PMID 37895153, 2023). "A previous study showed that IL-6 signaling plays an integral role in keloid pathogenesis." (PMID 35628356, 2022). "Furthermore, we found that differentiation of IL6+CSF3+ activated endothelial cells to MMP1+ endothelial cells activated by the NFΚB signaling pathway is a major feature of keloid vascular lesions." (PMID 36082167, 2022). "The IL-6 signaling pathway plays an essential role in keloid pathogenesis." (PMID 36406661, 2022). "Counter regulating the overexpression of IL-6 may be a key trigger factor to inhibit the prolongation of inflammatory phase in keloid wound healing." (PMID 33959031, 2021). "In HS and keloid, there is a relatively large number of studies on IL-6, IL-10 and IL-1β." (PMID 33959031, 2021). "UVA has a good effect in the overall treatment of keloid, but IL-6 and IL-8 were activated." (PMID 33959031, 2021). "Indeed, our data showing significant IL-6 up-regulation in keloids expands on previous studies that demonstrated elevated IL-6 expression in keloidal fibroblasts." (PMID 33329590, 2020). "In addition, proinflammatory factors, for example interleukin (IL)-1α, IL-1β, IL-6, and tumor necrosis factor-α are overexpressed in keloid, which proposes that the gene expression of these factors in the skin are responsive to trauma." (PMID 32850775, 2020). "The expression of IL-6 may be inherent to a feedback loop, wherein the increased expression of TGF-β promotes IL-6 production via PI3K and p38-MAPK, and IL-6 promotes TGF-β expression by keloid-resident macrophages." (PMID 32365896, 2020). "Moreover, proinflammatory factors, such as interleukin (IL)-1α, IL-1β, IL-6, and tumor necrosis factor-α are upregulated in keloid tissues, which suggests that, in patients with keloids, proinflammatory genes in the skin are sensitive to trauma." (PMID 28287424, 2017). "We then explored the interaction between IL-6 and IL-17 and determine whether the IL-17/IL-6 axis contributes to the regulation of the keloid niche." (PMID 19907660, 2009). "In summary, we have successfully identified multipotent precursor cells from keloid scars and provided evidence supporting IL-17/IL-6 axis as an essential component of the unique keloid niche that provides extra proliferation-promoting signals to resident stem cells." (PMID 19907660, 2009). "Taken together, these findings suggest that IL-6 and IL-17 are abundant components of the unique inflammatory niche of keloid and may contribute to the regulation of self-renewal and differentiation of keloid stem cells." (PMID 19907660, 2009). "Further studies are needed to determine whether the anti-scarring effect of the intralesional steroid therapy in keloid scar correlates with its role on the regulation of the IL-17/IL-6." (PMID 19907660, 2009). "Moreover, keloids feature a persistently inflamed microenvironment, with sustained infiltration of macrophages, mast cells, and T lymphocytes, along with elevated pro‐inflammatory cytokines such as IL‐1β, IL‐6, and TNF‐α." (PMID 41049267, 2025).
keloid (continued). "Additionally, EDN1 and NTF3 exhibited high correlations with fibrosis markers (COL1A1, TGFB1), inflammatory cytokines (IL6, TNFA), and immune cell infiltration (e.g., activated mast cells), suggesting their central regulatory roles in keloid-associated fibrosis and inflammation." (PMID 40051702, 2025). "Furthermore, treatment of keloid fibroblasts with the IL-6 receptor inhibitor, tocilizumab, decreased N-cadherin puncta, while IL-6 treatment of normal fibroblasts increased puncta, indicating that intercellular adhesion development is downstream of IL-6 signaling." (PMID 37660739, 2023). "Additionally, keloid formation is closely related to inflammatory responses, especially inflammation-related factors, such as interleukin 6, transforming growth factor-β, and tumor necrosis factor-α and inflammation-related cells, such as neutrophils, mast cells, and lymphocytes." (PMID 35967426, 2022). "Based on existing findings we asked whether IL-17 and IL-6 coordinately interact and contribute to the persistent local tissue inflammation in keloid, i.e. sustaining the “pathological” niche, therefore support the proliferation-promoting signal of the benign dermal growth." (PMID 19907660, 2009). "All together, our results suggest that the IL-17/IL-6 axis may function to maintain the highly elevated IL-6 level in the distinct keloid niche with abilities to regulate key stem cell functions such as hTERT and Oct-4 expression, thus contributing to the formation of the benign keloid growth." (PMID 19907660, 2009). "In our investigation, IL6 and HAS2 were identified as quercetin’s anti-keloid targets through network pharmacology." (PMID 41544047, 2026). "By inhibiting NF-κB activation, curcumin reduces the levels of cytokines such as IL-6 and TNF-α, decreasing inflammation and preventing fibroblast hyperproliferation in keloid tissue." (PMID 40741005, 2025). "These cells participate in various aspects of immune regulation during the development of keloids, such as the release of inflammatory mediators (e.g., interferon-γ(IFN-γ), IL-2, IL-6, TNF-α, IL-6, IL-10), as well as cell proliferation and migration." (PMID 40718487, 2025). "Excessive secretion of mature IL-18 by keloid coculture and increased expression of IL-18R in keloid fibroblasts lead to enhanced secretion of collagen-ECM components and profibrotic cytokines such as IL-6 and IL-8." (PMID 39799030, 2025). "Pro-inflammatory cytokines like IL-6, TNF-α, and IL-1β sustain chronic inflammation in the keloid tissue, further stimulating fibroblast activity and collagen production." (PMID 40741005, 2025). "Other metabolites, including quercetin and resveratrol, also exhibit anti-inflammatory effects by reducing IL-6 and TNF-α levels and decreasing inflammatory cell infiltration in keloid tissue." (PMID 40741005, 2025). "Tumor necrosis factor (TNF), IL-6, and IFN-β are upregulated in keloids, promoting cell migration and proliferation." (PMID 41562114, 2025). "In keloids, TGF-β upregulates the expression of anti-inflammatory cytokines like IL-10 while downregulating the levels of pro-inflammatory cytokines such as IL-6 and TNF-α, thus regulating the local immune microenvironment." (PMID 40718487, 2025). "In the context of keloids, the JAK-STAT pathway is activated by pro-inflammatory factors overexpressed in keloid tissues, such as IL-1β, IL-6, IL-17, and tumor necrosis factor (TNF)-α." (PMID 39201463, 2024). "This is supported by the upregulation of pro-inflammatory cytokines such as interleukin (IL)-1α, IL-1β, IL-6, and tumour necrosis factor (TNF)-α in keloid tissues." (PMID 39119435, 2024). "IL-6 and IL-17, in particular, have been shown to elicit STAT3 phosphorylation in both healthy and keloid fibroblasts." (PMID 39201463, 2024). "As the upregulation of IL-6 plays a role in keloid scars, we infer that IL1RN participates in the deposition of collagen via IL-6 signalling pathways." (PMID 37685578, 2023).
keloid (continued). "This revealed that inhibiting IL-6 signaling reduced both actin alignment and ECM anisotropy in keloid cells to levels observed in normal fibroblasts." (PMID 37660739, 2023). "Numerous cytokines, such as IL-4, IL-6, IL-10, IL-12, IL-13, IL-17, TNF-α, and TGF-β, are markedly elevated in the keloid local microenvironment." (PMID 37895153, 2023). "Indeed, isolated cultures of keloid fibroblasts show an increase in IL-6 secretion into the media, which led us to hypothesize that the enhanced alignment capacity of keloid conditioned media may be related to increased IL-6." (PMID 37660739, 2023). "TGF-β works in tandem with IL17A to stimulate IL-6 and CCL2 production in fibroblasts, which are macrophage chemokines and offer a way for macrophages to be recruited to the keloid microenvironment." (PMID 37895153, 2023). "We identified four subpopulations of endothelial cells in keloid and normal scar tissue by scRNA-seq data: MMP1+ Endo0, FOS + JUN + Endo1, IL6+CSF3+ Endo2, CXCL12 Endo3." (PMID 36082167, 2022). "The release of proinflammatory cytokines (interleukin (IL)-1, IL-6 and tumor necrosis factor (TNF)-α) in keloid tissues increases sensitivity to injury and upregulates these cytokines compared to the general population." (PMID 33413286, 2021). "It limits nodule growth by decreasing the expression of IL-6 and VEGF in keloid fibroblasts, and increasing the rate of fibroblast apoptosis." (PMID 32365896, 2020). "In vitro, the authors were able to show that the expression of IL-6 and TNF-α, as well as the production of α-SMA and collagen I, by human keloids fibroblast decreased after paclitaxel administration." (PMID 33343575, 2020). "Immunohistochemical staining showed IL-17, IL-1β, IL-6, and TNF-α level were increased in the perilesional area of keloids compared with normal tissue or the keloid intralesional area." (PMID 31814061, 2020). "We also examined secretion of a previously established wound healing mediator panel (CCL2, IL-6, CXCL8, VEGF, HGF and CCL27), which showed reduced HGF secretion in the reconstructed keloid model compared to the normal skin model." (PMID 31187196, 2019). "IL-6 and TGF-β1, which are elevated in KLs, promote differentiation of TH17 cells which then produce IL-17, further enhancing IL-6 release from keloid stem cells to influence the microenvironmental niche." (PMID 32039229, 2019). "Of interest, IL-6 and its second messengers JAK/Stat3, both of which are elevated in keloid fibroblasts, form the IL-6/JAK/Stat3 pathway, which contributes toward tumorigenesis within the tumor micro-environment." (PMID 31440236, 2019). "To recapitulate the “pathological” niche of keloid, we utilized a newly introduced carrier Extracel-HPTM Hydrogel conjugated with IL-6 for the in vivo transplantation of KPCs." (PMID 19907660, 2009). "Particularly, an elevated level of IL-6, a critical cytokine of the TH2 cells, and its receptor IL-6R, were detected in all keloid tissues screened and further confirmed by immunohistochemical studies and Western blot analysis." (PMID 19907660, 2009). "Subsequent network topology analysis through CytoHubba identified six hub genes (IL6, POSTN, VCAN, COL11A1, HAPLN1, TNC) via three methods of calculation respectively (Closeness, Degree and EPC), representing key regulatory nodes in the keloid." (PMID 41544047, 2026). "Additionally, they suppress pro-inflammatory cytokine production (IL-6, TNF-α) via NF-κB pathway inhibition, reducing the inflammatory environment that promotes keloid growth." (PMID 40741005, 2025). "Various pro‐inflammatory cytokines, including IL‐6, IL‐8, IL‐18 and chemokine like factor‐1 (CKLF‐1), are significantly elevated in keloid tissue, and IL‐8 and IL‐17 are elevated in the peripheral blood of keloid patients." (PMID 39895409, 2025).
keloid (continued). "Additionally, elevated levels of pro‐inflammatory cytokines such as IL‐1α, IL‐1β, IL‐6, and TNF‐α in keloids contribute to chronic inflammation by increasing fibroblast proliferation, inhibiting apoptosis, and driving ECM synthesis." (PMID 41049267, 2025). "Analysis of the keloid fibroblast transcriptome and protein levels upon IGFBP7 treatment revealed decreased levels of TGF-β1, Col I, VEGF, and pro-inflammatory markers interleukin-6 (IL-6) and interleukin-8 (IL-8), while levels of TGF-β3 were increased." (PMID 39045455, 2024). "The IL6 rs1800797, rs1800796, and rs1800795 and IL6R rs2228145 genotype distributions in the combined group of keloid patients and control newborns conformed to the expected Hardy-Weinberg equilibria (p = 0.364, p = 0.302, p = 0.368, and p = 0.674, respectively)." (PMID 38791322, 2024). "Inflammatory factors, such as IL-1α, IL-1β, IL-6, and TNF-α, are upregulated in keloid tissues, suggesting that keloids may be considered inflammatory skin disorders, specifically of the reticular dermis, rather than tumors." (PMID 39119435, 2024). "Furthermore, the mRNA and protein expression levels of gp130 and several downstream targets in IL-6 signaling (JAK1, STAT3, RAF1, and ELK1) were upregulated in keloid fibroblasts versus normal fibroblasts." (PMID 37895153, 2023). "Although shikonin inhibited the overproduction of IL-6 in keloid cells, it did not normalize the production of CXCL1." (PMID 34143844, 2021). "A plethora of factors including IL-6, IL-8, IL-18, chemokine like factor-1 (CKLF-1), prostaglandin produced by cyclooxygenase (COX-1) that exhibit pro-inflammatory roles upon tissue damage have been found significantly elevated in keloid tissue." (PMID 33343575, 2020). "Future clinical trials for keloid patients may include those targeting the Th2 axis, inhibitors of the TSLP-OX40 axis, antagonists of JAK/STAT-signaling, or IL-6 inhibition." (PMID 33329590, 2020). "In order to recapitulate the distinct “pathological” niche of keloid, we engineered the in vitro inflammatory niche by incorporating IL-6 non-covalently into the hydrogel carrier." (PMID 19907660, 2009). "With redox balance, TGF-β inhibits the production of pro-inflammatory cytokines such as TNF-α, IL-1β, and IL-6, stimulates IL-10, allows the differentiation of fibroblasts into myofibroblasts to help cover wounds, inhibits the TGF-β/Smad pathway and consequently reduces fibrosis and keloids." (PMID 39061892, 2024). "The rs1800797, rs1800796, and rs1800795 polymorphisms in the promoter of the IL6 gene coding for interleukin-6 and the rs2228145 polymorphism in the IL6R gene coding for the alpha subunit of the IL-6 receptor did not predispose to the occurrence of keloids in the studied group of Poles." (PMID 38791322, 2024). "To examine whether autocrine IL-6 production in keloid cells was initiating cell and ECM alignment, we treated normal and keloid cells with the IL-6 receptor blocking antibody, tocilizumab." (PMID 37660739, 2023). "In keloid scars, TGF-β1-induced overexpression in keloid keratinocytes of secreted factors, such as IL6 and WNT5A, may contribute to fibrosis directly, by stimulating signaling pathways in keloid fibroblasts that increase ECM production or indirectly by promoting an inflammatory microenvironment." (PMID 27574697, 2016). "Furthermore, treatment of keloid fibroblasts with tocilizumab inhibited the ability to remodel and align the ECM while treatment of normal fibroblasts with IL-6 increased ECM alignment revealing that IL-6 is both necessary and sufficient to induce fibroblast remodeling to align the ECM." (PMID 37660739, 2023). "However, CAF expression of IL-6 appears to require paracrine signaling from cancer cells and was reversible when cultured in monolayers, unlike keloid fibroblasts, suggesting that keloid cells may be uniquely reprogrammed to maintain high IL-6 expression." (PMID 37660739, 2023).